GAST (gastrin)
Diseases named in the same sentence as GAST in open-access papers (continued):
Sharing a sentence is not in itself a finding about the gene and the disease.
gastric neuroendocrine tumors (24 papers, 2013 to 2025). "Elevated gastrin levels stimulate enterochromaffin-like cell proliferation, raising concerns regarding the potential development of gastric neuroendocrine tumors or mucosal hyperplasia." (PMID 40777627, 2025). "Hypergastrinemia and gastric NETs develop secondary to the emergence of hyperplastic gastrin-expressing enteric glial cells in the duodenal lamina propria." (PMID 37492626, 2023). "Gastrin is considered to play a pivotal role in the development and progression of gastric neuroendocrine tumors." (PMID 37504250, 2023). "The three types of gastric neuroendocrine tumors have previously been described, as well as their relationship to gastrin levels." (PMID 33540736, 2021). "Recently, serum CEA levels have been recommended as a marker to evaluate the survival of patients with locoregional gastrin-independent gastric neuroendocrine tumors." (PMID 33738246, 2021). "Type III gastric NET are found in the setting of normal gastrin levels and exhibit a more aggressive behavior; they are treated surgically in a manner similar to adenocarcinoma: formal gastric resection and regional lymphadenectomy." (PMID 33540736, 2021). "The fundamental role of gastrin in the pathogenesis of gastric NETs was realized when similar tumours also occurred in patients with gastrinoma, causing Bordi to write a paper suggesting that these tumours were hormonally induced." (PMID 33266504, 2020). "The dominating role of gastrin in the pathogenesis of gastric NETs is demonstrated by their eradication by the treatment with the gastrin antagonist netazepide." (PMID 28144230, 2017). "Elevated circulating concentrations of the hormone gastrin contribute to the development of gastric adenocarcinoma and types-1 and 2 gastric neuroendocrine tumors (NETs)." (PMID 27323780, 2016). "Due to the unknown malignant potential of multiple pancreatic and gastric NETs, gastrin production short-acting SSA therapy (Octreotide 100 mcg/2 times daily) was initiated." (PMID 39682626, 2024). "Moreover, gastric NETs have been described in patients with elevated gastrin due to long-term treatment with inhibitors of gastric acid secretion, particularly proton pump inhibitors." (PMID 33266504, 2020). "More than 30 years ago, gastrin was realized to induce gastric NETs in man whether due to gastrinoma with increased gastric acid secretion or being secondary to hypoacidity causing Bordi to raise the question whether this was a hormone induced tumor." (PMID 28144230, 2017). "Moreover, since all conditions with long-term hypergastrinemia predispose individuals to gastric NETs, there is no need to claim that inflammation plays an additional role to gastrin in the pathogenesis of gastric NETs in patients with autoimmune gastritis." (PMID 34202596, 2021). "Netazepide, the gold standard for gastrin/CCK2R (cholecystokinin 2 receptor antagonists), has been tested in multiple trials for treating gastric neuroendocrine tumors and other conditions related to hypergastrinemia." (PMID 39598298, 2024). "According to a recently published paper, fasting 17-gastrin levels well correlate with the diagnosis of overt AIG and type 1 gastric neuroendocrine tumors." (PMID 35603187, 2022). "However, Mastomys, a hypergastrinemic rodent model that is genetically susceptible to spontaneous formation of gastric NETs, can develop gastric carcinoid tumor in the presence of normal serum gastrin levels, likely through the constitutive activation of CCK2R." (PMID 32210918, 2020). "In a previous study, it was found that employing a pepsinogen I/II ratio below 2.3 and gastrin-17 levels exceeding 29.6 pmol/L serves as a definitive approach to distinguish autoimmune gastritis patients with gastric neuroendocrine tumors from those without." (PMID 37504250, 2023). "In humans, gastrin is known to promote proliferation of ECL cells and pathogenesis of gastric NETs." (PMID 32210918, 2020).
Peptic ulcer (24 papers, 2008 to 2025). The term peptic ulcer refers to acid peptic injury of the digestive tract, resulting in mucosal break reaching the submucosa. "Gingerol treatment significantly enhances the secretion of gastrin and somatostatin, reducing the risk of peptic ulcer." (PMID 39234535, 2024). "In the UK Biobank, ABO, CDX2, CCKBRMUC1, MUC6, FUT2, PSCA, and GAST genes have been identified and found to be associated with peptic ulcer disease." (PMID 36678166, 2023). "Zollinger–Ellison syndrome (ZES) is an endocrinopathy caused by gastrin-secreting tumors responsible for the formation of multiple, refractory, and recurrent peptic ulcers localized in the distal duodenum and proximal jejunum and less commonly in the stomach." (PMID 34945075, 2021). "Our results suggest a role for Toll-like receptor 4 in gastric acid regulation and that the Toll-like receptor 4 +896 and +1196 wild type homozygozity increases peptic ulcer risk via gastrin secretion." (PMID 26161647, 2015). "The SGLT2I dapagliflozin may decrease risk of peptic ulcer by lowering blood glucose and modulating ghrelin, motilin, and gastrin levels, thereby decreasing gastric acidity and inflammation while promoting mucosal healing." (PMID 38856768, 2024). "In addition, hypercalcemia has been associated with acute pancreatitis and peptic ulcer diseases that could be explained by the hypercalcemia-induced activation of trypsin and gastrin secretions, respectively." (PMID 18976461, 2008). "Elevated serum gastrin levels, combined with a history of current or recent peptic ulcer disease and with diarrhea that is responsive to proton pump inhibitors (PPIs), support the diagnosis of ZES." (PMID 40941664, 2025). "The key mechanism in the pathogenesis of most peptic ulcers is thought to be H. pylori induced excessive gastrin secretion and the following excessive acid secretion, but the mechanisms of such aberration of regulation are unclear." (PMID 26161647, 2015). "We hypothesized that TLR4 could affect gastrin levels and thereby affect peptic ulcer pathogenesis also in human subjects." (PMID 26161647, 2015). "Adjunctive pharmaceutical management is also necessary, as the gastric remnant often continues to secrete gastrin after RYGB; thus, patients are often prescribed lifelong proton pump inhibitor (PPI) medication to reduce the occurrence of peptic ulcers." (PMID 40605885, 2025). "We speculate that TLR4–ligand interaction in G and D cells could have a direct effect in the gastrin and somatostatin secretion, respectively, and potentially explain the associations between the TLR4 polymorphisms and increased serum gastrin and the peptic ulcer risk." (PMID 26161647, 2015). "We believe our procedure is suitable for patients with GOO secondary to peptic ulceration and should be considered as one of the indications for surgical intervention in children with GOO with normal serum gastrin." (PMID 19123936, 2009).
pancreatic cancer (23 papers, 2006 to 2025). "Gastrin stimulates phosphorylation of paxillin, which is a focal-adhesion-associated kinase protein, prompting Golgi reorientation to the leading edge to promote migration of pancreatic cancer cells." (PMID 35563790, 2022). "Pancreatic cancer cells have been shown to co-express gastrin and its receptor, which have been postulated to be involved in autocrine/paracrine signaling contributing to pancreatic cancer cell growth." (PMID 40723238, 2025). "Gastrin is normally made in the G cells of the stomach antrum, but aberrant synthesis of gastrin is found in some gastrointestinal cancers, including pancreatic cancer, where gastrin stimulates growth by an autocrine mechanism." (PMID 36835036, 2023). "These NPs effectively down-regulated the expression of muKRAS and GAST; both have been shown to serve as drivers of pancreatic cancer." (PMID 36614194, 2023). "The polyplex nanoparticle platform used in this investigation was previously used to deliver GAST siRNA and was shown to decrease metastases in mice bearing human pancreatic cancers." (PMID 36614194, 2023). "In fact, down-regulating gastrin expression appears to be as effective in treating pancreatic cancer as down-regulation of muKRAS." (PMID 36614194, 2023). "For example, GNA12 together with GNA13 promotes gastrin-induced directional migration of pancreatic cancer cells via the cholecystokinin B receptor-GNA12/13-RhoA-ROCK signaling pathway." (PMID 37426201, 2023). "For example, the small, secreted molecule gastrin, which aids in regulating gastric acid secretion, is abnormally expressed in pancreatic cancer." (PMID 35563790, 2022). "Our long-term goal includes the development of this NP for diagnosis and, perhaps in combination with gastrin siRNA or other payloads, for treatment of PanIN lesions and prevention of pancreatic cancer." (PMID 34944412, 2021). "Gastrin has been shown to promote the reorientation of the Golgi apparatus and directional migration of pancreatic cancer cells by inducing the activation of paxillin." (PMID 34638432, 2021). "We previously demonstrated that this receptor-specific polyplex NP was selective in targeting the CCK-BR and delivering gastrin siRNA to successfully inhibit growth and metastases of human pancreatic tumors in mice." (PMID 34944412, 2021). "Downregulation of gastrin mRNA by RNA interference (RNAi) techniques inhibits the growth and metastasis of human pancreatic cancer." (PMID 34944412, 2021). "Recently, alphaV integrin, which is a new gastrin target gene in human pancreatic cancer cells, has been identified." (PMID 32784492, 2020). "The first mechanism—that is, increased gastrin production—has a carcinogenic effect on pancreatic cancer pathophysiology." (PMID 32784492, 2020). "In vitro and in vivo studies have shown that gastrin stimulates the growth of human pancreatic cancer cells through the gastrin receptor." (PMID 30208110, 2018). "Gastrin has been shown to stimulate the growth of human pancreatic adenocarcinoma and pancreatic cancer cell-lines." (PMID 21504585, 2011). "It binds with gastrin, tissue plasminogen activator, actin, and tenacin C and has been investigated as a serum and urine biomarker of pancreatic cancer." (PMID 21811618, 2011). "Targeting gastrin-induced cancer growth represents a novel therapeutic target for pancreatic cancer." (PMID 16622436, 2006). "It appears that gastrin stimulates growth of human pancreatic cancer by a receptor-mediated process and a unique CCK receptor exists in human pancreatic cancer that functions in growth, but is not found in normal human pancreas." (PMID 16622436, 2006). "In vitro and in vivo studies have demonstrated the inhibition of gastrin-stimulated growth of pancreatic cancer by gastrazole." (PMID 16622436, 2006).
pancreatic cancer (continued). "We previously showed that CCK-BR targeted NPs delivering a gastrin (GAST) siRNA payload could prevent pancreatic cancer metastases in mice bearing PANC-1 and BxPC-3 tumors when treatment with nanoparticles was initiated one week after tumor cell inoculation." (PMID 36614194, 2023). "In addition to mutant KRAS, other growth factors have been shown to stimulate growth of human pancreatic cancer, including gastrin." (PMID 36614194, 2023). "A cancer vaccine that induces neutralizing antibodies to gastrin was shown to improve survival in a murine model of pancreatic cancer and reduce metastases by decreasing components of the metastases cascade and EMT, including protein expression of paxillin, β-catenin, and MMP-7." (PMID 36614194, 2023). "This experiment shows that the GAST siRNA loaded NP is capable of improving survival and lowering metastases even when the treatment is started late, similar to that of many human subjects diagnosed in late stages with pancreatic cancer." (PMID 36614194, 2023). "However, gastrin also becomes re-expressed by microRNA-27a in PanINs and in pancreatic cancer, where it stimulates growth by an autocrine mechanism." (PMID 34944412, 2021). "Moreover, the following also supports the effects of gastrin as a growth factor for pancreatic cancer." (PMID 32784492, 2020). "However, polyclonal antibody stimulator (PAS), an anti-gastrin cancer vaccine, inhibits tumor formation, metastases of pancreatic cancer, and gastrin-induced EMT." (PMID 31952344, 2020). "Besides, gastrin also plays an important role in other cancers, such as pancreatic cancer 23 and other malignancies, such as natriuresis and diuresis." (PMID 28781948, 2017). "Apparently, an antisense oligonucleotide directed against gastrin mRNA inhibited growth of human pancreatic cancer cells up to 88% inhibition in a dose dependent fashion, supporting the role of gastrin as a growth regulatory peptide for human pancreatic cancer." (PMID 21504585, 2011). "Gastrin has been shown to be a growth stimulant in pancreatic cancer cells." (PMID 16622436, 2006). "Indeed, gastrin is related to pancreatic cancer tumorigenesis." (PMID 32784492, 2020). "Since gastrin and its receptor, the CCK-BR, become activated in precancerous PanINs and are over-expressed in pancreatic cancer, strategies to target this pathway have been investigated." (PMID 34944412, 2021). "Increased expression of gastrin and/or CCK were observed in human gastric adenocarcinoma, colorectal carcinoma, and pancreatic cancer, over that of the corresponding normal tissues, indicating potential roles of these peptides in promoting carcinogenesis." (PMID 32210918, 2020). "The autocrine production of gastrin and CCK are important for stimulating pancreatic tumor cell growth." (PMID 32210918, 2020). "In patients with pancreatic cancer, responders to gastrin-17-diphtheria toxoid immunogen (G17DT), which is an anti-gastrin antibody, showed a significantly longer survival than antibody non-responders." (PMID 32784492, 2020). "The pancreatic cancer cells produced both CCK and gastrin, however the CCK level was lower than the gastrin." (PMID 23077482, 2012). "The current view is that co-expression of gastrin and CCK2R (wt) regulates growth of human pancreatic cancer in an autocrine fashion." (PMID 21504585, 2011). "In contrast, pancreatic cancer cells and cell-lines expressed high levels of CCK2 and gastrin mRNA as well as gastrin peptides." (PMID 21504585, 2011). "It was claimed in a previous study that nearly all human pancreatic carcinomas studied expressed both CCK2R (wt) and gastrin mRNA." (PMID 21504585, 2011). "However, gastrin and their receptor (CCK-B/gastrin-like receptor) have a shared common link to develop pancreatic cancer." (PMID 36358776, 2022). "While down-regulation of gastrin inhibited growth of pancreatic tumor, change in the CCK level did not affect the tumor growth." (PMID 23077482, 2012).
pancreatic cancer (continued). "Smith and co-workers showed that antisense oligonucleotide to gastrin mRNA did not completely inhibit growth of human pancreatic cancer." (PMID 21504585, 2011). "In contrast, Ohlsson and co-workers reported that gastrin had no growth promoting effect on human pancreatic cancer cell-lines derived from pancreatic cancer biopsy specimens obtained at surgery." (PMID 21504585, 2011). "The purpose of the present investigation was to study CCK2R, CCK2i4svR, and gastrin mRNA expression in human pancreatic adenocarcinoma on the assumption that co-expression of CCK2R and gastrin or constitutive CCK2i4svR mRNA expression plays a pivotal role in the progression of pancreatic cancer." (PMID 21504585, 2011). "A local regulatory mechanism through gastrin and CCK2R, but no CCK mechanism, might be involved in pancreatic carcinoma." (PMID 32210918, 2020). "This would indicate that beside CCK2R/gastrin autocrine or paracrine growth loops, hitherto unknown CCK2R or gastrin induced pathways might be involved in stimulation of pancreatic cancer growth, which could explain the absence of co-expressed CCK2R (wt) and gastrin mRNAs in our study." (PMID 21504585, 2011).
colorectal cancer (21 papers, 2002 to 2025). A primary or metastatic malignant neoplasm that affects the colon or rectum. "For example, PPI use has been associated with inferior survival in colorectal cancer patients, possibly related to changes in fecal microbiota, increase in gastrin secretion with colonic polyp progression, and hypothetical endothelial function alterations." (PMID 37799958, 2023). "According to the mechanism of CRC development, many scholars advocates the viewpoints that a possible causal link between H. pylori infection, gastrin and colorectal cancer." (PMID 32704260, 2020). "Moreover, the study suggests that high levels of gastrin in hypergastrinemic mice are associated with an elevated risk of colorectal carcinoma." (PMID 38672239, 2024). "Previous studies have indicated that chronic hypergastrinaemia increases the risk of colorectal cancer and cancer growth and that interruption of the effects of gastrin could be a potential target in the treatment of colorectal cancer." (PMID 12189559, 2002). "Using our network-based approach, we found that the “Gastrin-CREB signaling pathway via PKC and MAPK” pathway was associated with the response to cetuximab treatment in colorectal cancer organoids." (PMID 33127883, 2020). "Our results did not demonstrate a statistically significant difference of serum gastrin levels in the colorectal cancer group compared to controls." (PMID 22719803, 2012). "Nevertheless, the exact significance of gastrin or its precursors in colorectal cancer is still a field of scientific investigation and safe conclusions cannot be reached yet." (PMID 22719803, 2012). "Another matter of conflict remains the possible correlation of gastrin levels and colorectal cancer stage." (PMID 22719803, 2012). "Nevertheless, it appeared that in colorectal cancer patients with infiltrated lymph nodes, the levels of gastrin were statistically significantly higher compared to the patients with no lymph node infiltrations." (PMID 22719803, 2012). "In this prospective case-control study, fasting serum samples from 93 consecutive patients with colorectal cancer treated in a university surgical clinic were preoperatively collected and serum levels of gastrin were measured." (PMID 22719803, 2012). "REG proteins are antiapoptotic and stimulate proliferation and repair, and apparently have roles in the trophic response to gastrin and in colorectal cancer." (PMID 21992413, 2011). "For example, haptoglobin and its glycosylated forms have been identified as potential biomarkers for non-small cell lung cancer and hepatocellular carcinoma, calcitonin for thyroid cancers, and gastrin for gastric and colorectal cancers." (PMID 19860894, 2009). "In contrast, the effectiveness of anti-gastrin antibodies in inhibiting tumour growth has been demonstrated in several animal models of colorectal cancer." (PMID 12189559, 2002). "In this study, when MC-26 colorectal cancer cells were incubated in the presence of gastrin, significant increases in COX-2 protein levels and COX-2 promoter activity was detected, compared with control conditions." (PMID 12189559, 2002). "The occurrence of most colorectal cancer is directly correlated to the abnormal gastrin expression." (PMID 36176299, 2022). "Finally, the effect of PPI on colorectal cancer was examined using a mouse model by inhibiting gastrin and YAP." (PMID 32485921, 2020). "In addition, the multivariable analysis showed that obesity, smoking history, alcoholism and diabetes mellitus have the strongest influence on the formation of colorectal cancer, while the level of gastrin didn’t show the influence." (PMID 32704260, 2020). "However, the number of the patients with the level of gastrin higher than 38.8 pm/L was 232 in in colorectal cancer group, and 19 in the control group, there was a significant difference between the two groups (P<0.05)." (PMID 32704260, 2020).